INS (insulin)
Diseases named in the same sentence as INS in open-access papers (continued):
Sharing a sentence is not in itself a finding about the gene and the disease.
Hyperglycemia (continued). "However, SIH is not only an epiphenomenon of severe stroke, but also an effector of further neuronal injury, as animal studies have shown that controlling hyperglycemia with insulin reduced the size of the ischemic lesion and improved functional outcomes after a stroke." (PMID 34064739, 2021). "While persistently hyperphagic db/db mice that overexpressed Yap in striated muscles continued to exhibit fasting hyperglycaemia and impaired whole-body glucose tolerance, fasting plasma concentrations of insulin and c-peptide levels were lower indicative of a reduction in insulin secretion." (PMID 34001905, 2021). "In addition, we suggest that insulin-related molecules partly mimicking insulin may block the insulin receptor, and thereby contribute to hyperglycaemia." (PMID 34170845, 2021). "Moreover, we present several lines of evidence to support that risperidone exacerbates hyperglycemia and that its reduction in GLUT4 expression and Akt phosphorylation in insulin signaling is associated with impaired glucose tolerance, increased IR, and decreased IS." (PMID 33401717, 2021). "In addition, the patient, required insulin to manage hyperglycemia secondary to steroids." (PMID 34490316, 2021). "Therefore, the progression of kidney diseases, including DKD, could be slowed or reversed by controlling hyperglycemia with insulin therapy." (PMID 34203830, 2021). "When the associations of anthropometric, glucose/insulin-related, and diet/exercise-related parameters with the CGM metrics were examined, the HbA1c and disposition index were significantly associated with all examined CGM parameters for hyperglycemia positively and negatively, respectively." (PMID 34578968, 2021). "In addition, this mixture of aqueous extract could modify hyperglycemia via elevating the level of insulin and regenerating β cells in the islets of Langerhans." (PMID 34867384, 2021). "Betulinic acid have been reported by several studies to effectively ameliorate hyperglycemia through inhibition of gluconeogenesis, elevation of the rates of cellular glucose uptake, inhibition of enzymes involved in glucose metabolism and the ability to normalize plasma glucose and insulin levels." (PMID 34567169, 2021). "However, insulin therapy controlled hyperglycemia may improve chronic inflammation condition in T2D patients." (PMID 34272768, 2021). "Additionally, critically ill patients may suffer from hyperglycemia necessitating the administration of insulin that drives the transport of phosphate into cells." (PMID 33763464, 2021). "A recent paper has shown that Alpk1-overexpressed C57BL/6 mice exhibited a decreased insulin level and severe hyperglycaemia than wild type mice after streptozotocin (STZ) treatment, suggesting that Alpk1 might participate in the destruction of pancreatic beta cells." (PMID 34621265, 2021). "In T2D and long exposure of β-cells to hyperglycemia and metabolic stress, cells tend to differentiate into immature, developmental expression program, which is characterized by low insulin content, poor insulin secretion, gene markers indicating a potential for proliferation." (PMID 33801681, 2021). "Whether hyperglycemia impair cognitive performance through insulin signaling need further study." (PMID 34512303, 2021). "Thus, the enriched Gram-negative pathobiont in women with GDM may enhance low-grade inflammation, impaired insulin signaling, and plasma glucose regulation, resulting in a hyperglycemia condition." (PMID 34681126, 2021). "Existing animal models with rod-dominant retinas have shown that hyperglycemia injures neurons, but it is not yet clearly understood how blue cone photoreceptors and retinal ganglion cells (RGCs) deteriorate in patients because of compromised insulin tolerance." (PMID 35046899, 2021). "Additionally, adenoviral ILDR2 knockdown led to reduced glucose-responsive insulin secretion in MIN6 β-cells, suggesting ILDR2 may be implicated in a new pathway in hypoinsulinemic hyperglycemia." (PMID 33863978, 2021).
Hyperglycemia (continued). "For example, ROS associated with several abnormalities, such as hyperglycemia, non-enzymatic glycosylation, inflammation and/or dyslipidemia, may cause decreased insulin expression and/or an impaired response to the insulin signal." (PMID 33893069, 2021). "However, more recent studies have shown that blocking the glucagon receptor in absolute insulin deficiency does not prevent hyperglycemia, indicating that residual insulin signalling is required in order for glucagon receptor antagonism to be effective." (PMID 34659118, 2021). "As hyperglycemia and elevated free fatty acids persist, an increase in reactive oxygen species (ROS), increases in intracellular calcium, and endoplasmic reticulum-related stress all contribute to the impairment of insulin secretion and, ultimately, apoptosis in β-cells." (PMID 34199898, 2021). "This is a chronic metabolic disorder characterized by a defined phenotype (hyperglycemia accompanied by greater or lesser impairment in the metabolism of carbohydrates, lipids, and proteins), triggered by either lack of insulin secretion or decreased sensitivity of the tissues to insulin." (PMID 34295913, 2021). "However, EVOO may account for the improved post-prandial hyperglycemia independently from the GER due to its intrinsic antioxidant properties improving the insulin signaling cascade." (PMID 34371945, 2021). "Authors concluded that the cardioprotective effects of insulin might by abrogated by hyperglycemia." (PMID 34445586, 2021). "In addition, concurrent with reduced insulin secretion, an imbalance in the insulin-glucagon axis during hyperglycemia with a reduced glucose-induced glucagon suppression has been described in a study that included Caucasian kidney transplant patients with PTDM." (PMID 34198724, 2021). "Finally, a multivariate linear regression analysis was also performed with a backwards strategy, introducing COVID-19 diagnosis, the presence of stress hyperglycemia, the need for insulin infusion, age, and sex as independent variables and ICU stay as the dependent variable." (PMID 34578888, 2021). "Furthermore, our results showed that LPI induced a recovery of insulin sensitivity and a subsequent decrease in hyperglycemia, a finding that may have involved the activation of hepatic glycogenesis." (PMID 34026071, 2021). "Polyphenols such as gallic acid and rutin, found abundantly in plants, may beneficially influence hyperglycemia by inhibiting digestive enzymes (amylase and glucosidase), stimulating insulin secretion from the β cells of the pancreas, and decreasing blood glucose levels." (PMID 34961044, 2021). "In addition, insulin resistance, disturbed insulin secretion, and pancreatitis are the consequences of OP exposure, which might explain the hyperglycemia recorded in this poisoning." (PMID 33672765, 2021). "Pancreas-specific SIRT1 deficiency results in lower insulin secretion by β-cells, but is not accompanied by hyperglycemia, suggesting that a compensatory mechanism may exists." (PMID 33806509, 2021). "While this works to reduce hyperglycemia in these patients, the concept of treating an insulin resistance disease by increasing insulin levels may be counterproductive, as it may later necessitate an increase in the dosage of medication over a long period of time (for review, please see:)." (PMID 33921979, 2021). "Similarly, some reports indicated that low-dose insulin, which is insufficient in reducing hyperglycemia, may have a beneficial effect on the signs and symptoms of DPN." (PMID 34071138, 2021). "Therefore, we speculate that when faced with sustained hyperglycemia, islet cells exert plasticity favoring dedifferentiation, possibly potentiated by insulin resistance." (PMID 33427207, 2021). "In addition, Cer16:0 decreased hepatic insulin signaling in mice, leading to hyperglycemia." (PMID 33276146, 2021).
Hyperglycemia (continued). "Polyphenols derived from olive products may be responsible for these beneficial effects since they are reported to improve metabolic insulin sensitivity and alleviate some of the manifestations of metabolic syndrome, including arterial hypertension and hyperglycemia." (PMID 34356299, 2021). "Consequently, when the fetus has not inherited the maternal mutation, maternal hyperglycemia will trigger increased fetal insulin secretion and growth, with a high risk of macrosomia." (PMID 35069449, 2021). "The literature recommends the preferential use of IC, even at higher doses, thus being possible to reduce the chances of glycemic lack of control, since the use of systemic corticosteroids may result in hyperglycemia or the deterioration of glycemic control, requiring progression to insulin therapy." (PMID 33520042, 2021). "Mechanistically, we postulate that a reduced insulin secretion due to the KCC2-NKCC1 imbalance subsequent to acute oxygen desaturation could result in hyperglycemia in rat pups, paralleling symptoms shown in patients with COVID-19 who experienced acute respiratory distress." (PMID 34943374, 2021). "Moreover, evidence regarding tricyclic antidepressants such as doxepin and amitriptyline has indicated that hyperglycemia develops from pancreatic insulin release being inhibited and that tricyclic antidepressant use inhibits glucose transport, resulting in decreased glucose uptake." (PMID 33809508, 2021). "The identification of an association between decreased ILDR2 expression in β-cells and decreased insulin secretion may potentially represent a component of a new pathway in hypoinsulinemic hyperglycemia and provide a new mechanism for decreased insulin secretion." (PMID 33863978, 2021). "Moreover, in a more conservative in vivo model (T1DM), plant-derived polyphenol extract mixture was more effective towards ameliorating hyperglycemia, hyperlipidemia and histopathological decline in pancreas, kidney and liver compared to standard medication (insulin and metformin)." (PMID 34501954, 2021). "In addition to direct regulation of the immune system, IL-37 is also correlated with insulin sensitivity, which could contribute to the uncontrolled hyperglycaemia status in GDM women." (PMID 34513891, 2021). "Indeed, defects of the GCK gene cause a higher glycaemic set point of insulin secretion resulting in mild fasting hyperglycaemia, in contrast to other subtypes which are characterized by impaired insulin secretion and high glycaemic response after meals and during OGTT." (PMID 34496959, 2021). "Finally, it was suggested that black mulberry leaves could be used to control hyperglycemia as they increased the serum insulin level and present hepatoprotective action given the attenuated liver damage markers." (PMID 33498684, 2021). "Hyperglycemia and high intracellular glucose metabolism, a hallmark of T2DM, is associated with excessive mitochondrial reactive oxygen species (ROS) and oxidative stress, which can impair insulin signaling and lead to insulin resistance of skeletal muscle glucose transport." (PMID 33924335, 2021). "Furthermore, OS from hyperglycemia may promote β-cell dysfunction and reduce insulin secretion by β cells." (PMID 33928135, 2021). "Due to hepatic insulin resistance, this hormone losses its ability to regulate glucose metabolism in liver, resulting in enhanced glucose output that contributes greatly to fasting and postprandial hyperglycemia, namely glycogen synthesis is reduced, and production of glucose is increased." (PMID 35002743, 2021). "However, in comparison with saline-treated T1D mice, once-daily insulin detemir treatment failed to control blood sugar well or recover weight loss but reduced deaths due to hyperglycemia." (PMID 34975749, 2021).
Hyperglycemia (continued). "However, increased expression and secretion of VEGF facilitates hypervascularization and infiltration of macrophages in pancreas, which secrete proinflammatory cytokines (e.g., TNF-alpha, IL6) that impair insulin secretion decrease beta-cell mass, and promote hyperglycemia." (PMID 34948944, 2021). "Without suitable treatment, persistent hyperglycemia may cause glucose toxicity, which may gradually damage the secretion of insulin." (PMID 34071977, 2021). "Furthermore, hyperinsulinemia and hyperglycemia affect insulin-signaling pathways." (PMID 34203572, 2021). "The automation of insulin delivery in response to real-time sensor glucose levels reduces the need for user input, and events such as post-prandial hyperglycaemia or exercise-induced hypoglycaemia may be prevented or attenuated by the closed-loop system itself." (PMID 33996702, 2021). "In contrast, other authors have suggested that hyperglycemia may not cause dyslipidemia, but rather abnormalities in insulin action, and hence, a hypoglycemic effect may not improve the lipid profile per se." (PMID 33918509, 2021). "It is well recognized that Slc2a4 knockout induces hyperglycemia, whereas the overexpression of Slc2a4 improves glycemic control even in DM mice, regulations that were directly associated with the amount of GLUT4 at the PM, independently of changes in insulin signaling." (PMID 35011666, 2021). "Its also worth noting that intensive insulin therapy is the standard of care for all critically ill patients, regardless of underlying disease, with the aim of reducing hyperglycaemia associated with the acute phase of injury which facilitates inflammation and sepsis." (PMID 34282152, 2021). "Liver represents a crucial therapeutic target for treating hyperglycemia in T2D because hepatic glucose output is the pathophysiological abnormality that contributes the most to the hyperglycemic state in fasting and postprandial state as a consequence of hepatic insulin resistance." (PMID 35002743, 2021). "The results revealed that SDG significantly reduces hyperglycemia while controlling the blood glucose and serum lipid intensities, regulating the metabolic equilibrium, and maintaining tissue function, leading to improved sensitivity and response of target cells to insulin." (PMID 33440620, 2021). "However, the odds of hyperglycemia was higher in participants who were on metformin and vildagliptin compared with participants who were on metformin and glimepiride or metformin, insulin glargine U100, and human regular insulin." (PMID 34305809, 2021). "However, while past studies explored chronic dysglycemia and the acute and selective effect of hyperglycemia in the presence of insulin, little is known about the effect of acute periods of insulin deficiency and resulting altered metabolic milieu on the brain." (PMID 33561011, 2021). "Both insulin infusion with subsequent hypoglycemia and the euglycemic clamp cause a ghrelin decrease, indicating the main regulator role of hyperinsulinemia, rather than hyperglycemia, on ghrelin." (PMID 34199514, 2021). "Moreover, knockout of Nt5c2 (in mice) not only protects against high-fat diet-induced weight gain and adiposity but also improves insulin sensitivity and reduces hyperglycemia, all in line with our observation of improved healthspan and lifespan in C. elegans treated with RNAi against Y71H10B." (PMID 34492009, 2021). "Furthermore, acute activation of Myc in pIns-c-MycERTAM transgenic mice initially results in highly increased serum insulin levels and subsequent hypoglycemia, whereas chronic activation of Myc in these mice leads to a significant decrease in serum insulin, resulting in hyperglycemia." (PMID 33239359, 2021). "Notably, treatment with metformin, insulin, or a combination of both was associated with failure to normalise glucose levels in all patients and the hyperglycaemia observed was more pronounced in patients with T2D and high CRP levels." (PMID 35844722, 2021).
Hyperglycemia (continued). "MODY can be suspected when hyperglycemia is detected in patients under 25–35 years of age, there is little or no need for insulin, secretion of C-peptide is intact, β-cell antibodies are absent, and dysfunction of pancreatic β-cells results in a decrease in the insulin amount." (PMID 33477506, 2021). "In addition, our results could contribute to improve the automated insulin given system, adding new oscillatory pattern, possibly contributing to determine the hour and magnitude of hypo and hyperglycemia events in DM patients." (PMID 33707491, 2021). "The other possible cause of HFD induced increased body weights, hyperglycemia and dyslipidemia in the current study is the reduction of leptin, adiponectin and UCP1 protein expression, which play important roles in the regulation of food intake, insulin sensitivity and energy metabolism." (PMID 32197395, 2020). "Dietary intake of genistein (250 mg/kg diet) improved hyperglycemia, glucose tolerance, and blood insulin level in obese diabetic mice, whereas it did not affect body weight gain, food intake, fat deposit, plasma lipid profile, and peripheral insulin sensitivity." (PMID 33255206, 2020). "Thus, hyperglycemia and insulin fail to inhibit lipolysis and glucose production." (PMID 33251224, 2020). "However, other GABAergic neuronal groups likely contribute to glucose-lowering effects as well, because intracerebroventricular (i.c.v.)leptin injection still can lower hyperglycemia in insulin-deficient mice lacking LEPRs in AgRP neurons." (PMID 33071988, 2020). "However, it has been suggested that serum levels of GPLD1 may be regulated by a number of different hormones or metabolites involving circulating insulin levels, hyperglycemia, oxidative stress, and inflammation." (PMID 32467736, 2020). "Taken together, the data from previous and present research implicated failure of adipsin (or the adipsin pathway) to rise in response to acute hyperglycemia, which could be responsible at least in part for inadequate insulin increase in acute hyperglycemia in T2D." (PMID 33233515, 2020). "With the insulin-independent glucose uptake in skeletal muscle increasing acutely by muscle contractions, an exercise bout could attenuate the amplitude and duration of the post-prandial hyperglycemia when performed in continuation of a meal." (PMID 32903679, 2020). "While insulin dose adjustment is a critical component of decision support, people with T1D also need to be notified about impending acute glucose changes that could lead to dangerous hypo- or hyperglycemia." (PMID 32517068, 2020). "Likely off-target recombination was not concerning because there are no other tissues that could reasonably cause hyperglycemia following loss of the insulin gene." (PMID 32601405, 2020). "Because hepatic insulin signaling regulates the activity of transcription factors involved in gluconeogenesis, glycolysis, and fatty acid synthesis, insulin resistance in the liver increases glucose production in the liver, resulting in fasting hyperglycemia or lipoprotein production." (PMID 33005239, 2020). "In addition, as our focus was on hypoglycemia, although some insulin regimens have a less hypoglycemic effect, this could be at the expense of having hyperglycemia, which is beyond the scope of this research." (PMID 32133264, 2020). "Developing type 1 diabetes secondary to immunotherapy poses a risk for recurrent hyperglycemia and DKA such that once patients lose endocrine pancreatic function and are insulin dependent, they may continue immunotherapy for lethal malignancies, as pancreatic damage is likely irreparable." (PMID 32733645, 2020). "Moreover, in subjects with diabetes, the delay in gastric emptying and intestinal glucose absorption after a meal by α-glucosidase inhibitors or somatostatin, improved time differences between postprandial plasma glucose and insulin increases, thus leading to lower postprandial hyperglycemia." (PMID 32532002, 2020).